IRX2 (iroquois homeobox 2)
Diseases named in the same sentence as IRX2 in open-access papers (continued):
Sharing a sentence is not in itself a finding about the gene and the disease.
sarcoma (1 paper, 2017). A usually aggressive malignant neoplasm of the soft tissue or bone. "Genes located in 5p that have been suggested as possible amplicon targets in sarcomas include NKD2, TERT, IRX2, TRIO, AMACR, SKP2 and RICTOR." (PMID 28652867, 2017).
skin cutaneous melanoma (1 paper, 2023). "Higher expression of IRX1, IRX2, IRX3, IRX5, and IRX6 all display statistically significant unfavorable prognosis for skin cutaneous melanoma." (PMID 37084727, 2023).
soft tissue sarcoma (1 paper, 2008). A malignant neoplasm arising from muscle tissue, adipose tissue, blood vessels, fibrous tissue, or other supportive tissues excluding the bones. "Also, IRX2, involved in the regulation of developmental processes via the WNT pathway and which is notably amplified in soft tissue sarcomas was overexpressed." (PMID 18545673, 2008).
tumor (19 papers, 2009 to 2025). "The loss of IRX2 expression at the primary tumor might therefore contribute to bone metastasis formation by mobilizing cells and rendering them for dissemination." (PMID 26560478, 2015). "IRX-2 helps overcome tumor-mediated immunosuppression by acting on multiple immune cells such as DCs, NK, and T cells." (PMID 33925575, 2021). "The expression level of IRX2 in the tumor samples resulted in line with that observed in the normal brain sites." (PMID 29568396, 2018). "We also identified Iroquois Homeobox 2 (IRX2) as the master regulators for an expression of SPP1-encoded osteopontin, a secreted stromal driver for tumor growth that is overexpressed by both RS and SIPS fibroblasts." (PMID 28105936, 2016). "Most of these studies have not performed functional validation of the exact biological role of the IRX2 in tumor progression." (PMID 26560478, 2015). "Low IRX2 mRNA expression was found to be correlated with high tumor stage (p = 0.004), high tumor grade (p < 0.001) and the presence of lymph node metastasis (p = 0.044)." (PMID 26560478, 2015). "Surprisingly, lower IRX2 mRNA expression was also significantly correlated with smaller tumor size (p = 0.05)." (PMID 26560478, 2015). "During our analysis the most prominent differences connected with the location of the tumor were noted for the IRX2, PAX3, CXCL14, LHX2, SIX6, CNTN1 and SIX1 genes." (PMID 26497896, 2015). "Another fusion transcript involving IRX2 and TERT, caused by an interstitial deletion of 5p, was recently reported in a single tumor classified as CCSK." (PMID 26158413, 2015). "IRX-2 is a primary cell-derived cytokine biologic that enhances immune response and induces tumor rejection in preclinical studies." (PMID 24213121, 2011). "IRX-2 acts on T cells by preventing tumor-induced apoptosis and enhances its effector function, particularly in regional lymph nodes, to reinvigorate both innate and adaptive host immunity in the battle against tumor cells." (PMID 34277428, 2021). "Furthermore, we evaluated the expression levels of selected differentially methylated genes and identified two biomarkers, one, IRX2, related to the tumor localization and the other, TOX2, as tumoral biomarker." (PMID 29568396, 2018). "Additionally, we identified Iroquois Homeobox 2 (IRX2) as a master regulator for the secretion of SPP1-encoded osteopontin, a stromal driver for tumor growth that is overexpressed by both RS and SIPS fibroblasts." (PMID 28105936, 2016). "Moreover, Iroquois Homeobox 2 (IRX2) was highlighted as a master regulator for the secretion of SPP1-encoded osteopontin, a stromal driver for tumor growth that is overexpressed by both RS and SIPS fibroblasts." (PMID 28105936, 2016). "The ability of IRX-2 to activate both DCs and T and even B and NK cells makes it especially attractive since it is this combination of immune cell subsets that coordinate the immune response against tumor antigen expressing cells." (PMID 24213121, 2011). "IRX-2 is an immune modulator with demonstrated preclinical and clinical pleiotropic immune activities including enhancement of the immune response to potential tumor antigens." (PMID 24213121, 2011). "In addition to influencing T cell proliferation and differentiation, IRX-2 has also been shown to reverse tumor induced death of T cells thus providing an additional mechanism of action for IRX-2 in a tumor vaccine model." (PMID 24213121, 2011). "The delivery of cytokines, either by single cytokines, for example, interleukin-2, interleukin-12, interferon-γ, interferon-α, or by a biologic mix of multiple cytokines, such as IRX-2, may result in tumor rejection and durable immune responses." (PMID 19680453, 2009). "Collectively, the expression status of IRX2, SPINK13, and CAPN8 was in line with our findings in scRNA‐seq that they all showed an elevation both in tumor tissues and cells, which was also coincided with the development of tumor stage in LUAD." (PMID 35102706, 2022).
tumor (continued). "Three genes in the model, IRX2, SPINK13, and CAPN8, were also validated with their expression and potentials in tumor proliferation." (PMID 35102706, 2022). "IRX2 and TOX2 gene expression levels in tumor samples were compared to commercially available human normal brain samples and to GTEx expression data observed in different normal brain sites." (PMID 29568396, 2018). "The upregulation of other homeobox transcription factors was also observed by us in cases of infratentorial tumor, which was shown to be connected with Iroquois homeobox transcription factors (IRX1, IRX2, IRX3, IRX5) and the PAX3 gene." (PMID 26497896, 2015). "However, CD40, glypican 3 (GPC3), Iroquois homeobox 2 (IRX2), FOXO1, EPAS1, and cyclin-dependent kinase inhibitor 1C (CDKN1C) were consistently down-regulated in tumor tissues and GbPDTOs compared to those in normal tissues." (PMID 41376821, 2025). "Moreover, we found that IRX2, SPINK13, and CAPN8 showed great superiority to their counterparts in differentiation, especially in the ability to distinguish malignant tumor cells from normal epithelial cells." (PMID 35102706, 2022). "Our results signaled that IRX2, SPINK13, and CAPN8 could serve as novel therapeutic targets to prevent tumor growth in LUAD." (PMID 35102706, 2022). "To explore whether IRX2 and TOX2 may also have an impact on tumor prognosis, we performed a survival analysis using a web-tool called PROGgeneV2." (PMID 29568396, 2018). "All this evidence adds up in favor of the hypothesis that SPP1/osteopontin expression may be controlled by IRX2, and that its derepression in senescent fibroblast aids in SIPS-dependent stromal activation that, in turn, stimulate the growth of tumor cells." (PMID 28105936, 2016).
cancer (8 papers, 2011 to 2025). A tumor composed of atypical neoplastic, often pleomorphic cells that invade other tissues. "For eribulin, IRX2 is a homeobox gene important in normal embryonic development and has been implicated in cancer, while C5ORF38 is coordinately regulated with IRX2, suggesting both are involved in cellular differentiation and growth regulation." (PMID 36139690, 2022). "In addition to increasing the activation of DCs as measured by surface expression of many activation markers, IRX-2 reversed the depressed antigen processing activity of dendritic cells from cancer patients." (PMID 24213121, 2011). "Differentially methylated CpGs related to NXPH4 and LBX2 have previously been described in a study that developed a placental epigenetic clock, whereas aberrant methylation and/or expression of NXPH4, EPS8L2, AMOTL1, IRX2, and LBX2 have also been described in multiple types of cancers." (PMID 40338255, 2025).
infection (3 papers, 2023 to 2025). The state of being infected such as from the introduction of a foreign agent such as serum, vaccine, antigenic substance or organism. "Cre infection led to an ∼87% reduction in IRX2 protein expression in vitro." (PMID 37587150, 2023). "Other genes that increased infection efficiency by ≥4-fold upon knockout included MOSPD2, P4HB, and LY6E (each leading to an approximately 4-fold increase) and IRX2 (an approximately 8-fold increase)." (PMID 40901862, 2025).
IRX2 also shares sentences with these, for which no sentence is quoted: B-cell precursor acute lymphoblastic leukemia (2 papers); adenoma (1); breast invasive carcinoma (1); craniosynostosis (1); ependymoma (1); glioma (1); heart failure (1); infratentorial tumors (1); kidney clear cell sarcoma (1); Kyphoscoliosis (1); lymph node metastasis (1); Obesity (1); optic atrophy (1); osteoporosis (1); T-cell ALL (1).